EGFR (epidermal growth factor receptor)
Diseases named in the same sentence as EGFR in open-access papers (continued):
Sharing a sentence is not in itself a finding about the gene and the disease.
lung adenocarcinoma (continued). "The present case demonstrated that osimertinib could be a possible treatment option for EGFR exon 20 insertion-positive lung adenocarcinoma." (PMID 31645848, 2019). "In this study, we analyzed CT imaging-based histogram features of bone metastases with and without EGFR mutation in patients with primary lung adenocarcinoma." (PMID 31174617, 2019). "TTF-1 expression was a good prognostic indicator for OS and PFS in stage IV lung adenocarcinoma patients with and without EGFR-sensitizing mutations." (PMID 31196060, 2019). "Our present study indicated that TTF-1 expression was a good prognostic indicator for OS and PFS in patients with stage IV lung adenocarcinoma regardless of the presence or absence of EGFR mutations." (PMID 31196060, 2019). "Another reason why the difference between EGFR Mut and WT in terms of smoking status is diminished may be that the incidence of lung adenocarcinomas in female was higher than male." (PMID 31993370, 2019). "This study aims to clarify the significance of MMP-1 in EGFR-TKI–resistant lung adenocarcinoma." (PMID 29463039, 2018). "Several studies have reported that gefitinib might be a soothing choice for the initial treatment of patients with EGFR-mutant lung adenocarcinoma and newly diagnosed brain metastases." (PMID 30458751, 2018). "However, to the best of our knowledge, no reports have studied the functions of matrix metalloproteinases (MMPs), one of the well-characterized factors in the promotion of invasion and migration in EGFR-TKI–resistant lung adenocarcinoma cells." (PMID 29463039, 2018). "The epidermal growth factor receptor (EFGR) mutation was closely related to the invasion and metastasis of lung adenocarcinoma and the biological axis of CXCR4/CXCL12 (chemokine receptor 4/chemokine ligand 12) played an important role in the organ-specific metastasis of the tumor." (PMID 30037369, 2018). "Since EGFR proteins were responsible to platinum-based chemotherapy, treatment selection according to EGFR expression might be essential in the treatment of lung adenocarcinoma patients." (PMID 29950164, 2018). "EGFR proteins at different cellular locations in lung adenocarcinoma might influence the biology of cancer cells and are an independent indicator of more favorable prognosis and treatment response." (PMID 29950164, 2018). "This present study indicated that differentially located EGFR proteins might serve as a molecular marker of survival outcomes in patients with lung adenocarcinoma." (PMID 29950164, 2018). "Particularly interesting were the results of a study performed by Hong and coworkers based on the screening of a total 1160 Chinese NSCLC patients: 78% lung adenocarcinomas, 54% never-smokers, 33.8% with EGFR mutations and 8.1% with EML4-ALK rearrangements." (PMID 30060526, 2018). "EGFR plays an essential role in regulating cell proliferation and apoptosis of lung adenocarcinoma." (PMID 29788985, 2018). "Nevertheless, high EGFR expression may predict the response to gefitinib in lung adenocarcinoma with a high survival and provide survival benefits when gefitinib is used in combination with cetuximab in advanced NSCLC with wildtype EGFR status." (PMID 29950164, 2018). "We first focused on PC-9/NaqR cells derived from PC-9, EGFR-TKI-naïve lung adenocarcinoma cells." (PMID 29386539, 2018). "Therefore, we suggest that differentially located EGFR expression synergistically predict survival outcomes and treatment responses in lung adenocarcinoma patients." (PMID 29950164, 2018). "There is thus an unmet need both to identify agents that may impede resistance to EGFR inhibitors in adenocarcinoma of the lung, as well as to to identify new therapeutic targets for SCC." (PMID 29581842, 2018). "Thus, carcinoembryonic antigen levels and EGFR genotype should be considered together to assess prognosis in pathological T1 lung adenocarcinoma." (PMID 29849818, 2018).
lung adenocarcinoma (continued). "Some previous reports have stated that MMP-1 promotes the invasion ability of cancer cells, including A549, a lung adenocarcinoma cell without EGFR mutation." (PMID 29463039, 2018). "In particular, the small molecule EGFR TKI inhibitors, erlotinib and gefitinib show dramatic activity in EGFR-mutated lung adenocarcinomas and the anti-ErbB2 antibody, trastuzumab and the dual EGFR/ErbB2 inhibitor, lapatinib have proven benefits in ErbB2-amplified malignancies." (PMID 29861842, 2018). "Unlike lung adenocarcinoma, activating mutations in EGFR and ALK fusion are typically not present in LSCC, so targeted agents are largely ineffective against LSCC." (PMID 29456509, 2018). "Therefore, a liquid biopsy such as cell-free plasma DNA (cfDNA) is used for molecular testing with advanced technologies for patients with advanced lung adenocarcinoma following EGFR-TKI treatment failure." (PMID 30444875, 2018). "In contrast, in lung adenocarcinoma patients treated with EGFR tyrosine kinase inhibitors and platinum-based doublet chemotherapy, carcinoembryonic antigen levels > 5 ng/mL were associated with unfavourable prognosis in patients without EGFR mutations, but not in patients with EGFR mutations." (PMID 29849818, 2018). "The development of targeted cancer therapies has led to improved results in the metastatic setting for patients with lung adenocarcinomas which bear oncogenic driver alterations, such as epidermal growth factor receptor (EGFR) and re-arranged anaplastic lymphoma kinase (ALK)." (PMID 30416904, 2018). "EGFR mutations are the most common genetic alterations in lung adenocarcinoma and are more frequent in women, never smokers, and Asian patients." (PMID 29518290, 2018). "Although the prognostic impact of EGFR mutation in lung adenocarcinoma remains controversial, several retrospective studies have reported that patients with EGFR mutation survived for longer periods than those without mutations, irrespective of therapy." (PMID 29343775, 2018). "The Nrf2 positive rate significantly correlated with gender, stage and status of EGFR gene mutation (P < 0.05), but not with age, smoking, differentiation and subtype of lung adenocarcinoma (P > 0.05)." (PMID 29587953, 2018). "Furthermore, the data from randomized controlled trials(RCTs) and other investigations have also indicated that EGFR-TKI has advantageous when used as an initial treatment for Asian patients with EGFR-mutant lung adenocarcinoma and brain metastases." (PMID 30458751, 2018). "The effect of CSD on PFS and overall survival (OS) in patients with EGFR-mutated lung adenocarcinoma is yet to be clarified, and only few studies have directly focused on the relationship between the efficacy of EGFR-TKI and CSD in patients with EGFR-mutated lung adenocarcinoma." (PMID 30055587, 2018). "To investigate the potential molecular mechanisms of EGFR over-expression and EFGR-mutations effects on cell proliferation, migration and invasion, we constructed EGFR over-expression and three EFGR-mutant human lung adenocarcinoma H1299 cell sublines." (PMID 30037369, 2018). "More importantly, NEDD4 and EGFR are always co-expressed in lung adenocarcinoma tumor tissue, suggesting that NEDD4 might be associated with EGFR in lung adenocarcinoma." (PMID 29455656, 2018). "Thus, targeted treatment is now approved for patients with EGFR-mutated and ALK-rearranged advanced lung adenocarcinomas." (PMID 30060526, 2018). "Although lung adenocarcinoma with activating epidermal growth factor receptor (EGFR) mutations is common in never smokers, one-third of the patients are ever-smokers." (PMID 30055587, 2018).
lung adenocarcinoma (continued). "Lung adenocarcinoma (LUAD) cases with actionable mutation of EGFR are discriminable from those without by protein profile (sdis = − 0.44; p = 5.9e−4; srand = 3.1e−5)." (PMID 30442178, 2018). "The most common mutation in lung adenocarcinoma in never smokers is EGFR and its incidence varies depending on gender and ethnicity being the highest in East Asian females (~78%), followed by Caucasians (43–51%) and South Asians (29%)." (PMID 29854298, 2018). "Because of the important role that EGFR plays in many lung adenocarcinomas, several drugs have been developed that specifically target the EGFR pathway, including EGFR-inhibiting antibodies (cetuximab) and small molecule tyrosine kinase inhibitors (erlotinib, gefitinib, afatinib)." (PMID 30408128, 2018). "Moreover, more studies that compared both OS and PFS between erlotinib and gefitinib in stage IV exon 19 EGFR-mutant lung adenocarcinoma patients after completion of all standard adjuvant chemotherapy and/or radiation therapy also showed similar outcomes." (PMID 30458751, 2018). "CRKL amplification was detected in EGFR-TKI-treated lung adenocarcinoma patients." (PMID 30445769, 2018). "Alterations in EGFR, as well as in other genes such as KRAS mutations or ALK translocations, are frequent in lung adenocarcinoma; all these changes have been involved in the activation of signaling pathways critical in lung tumorigenesis, such as MAPK and PI3K/AKT pathways." (PMID 29731995, 2018). "Therefore, in this study, the focus is on the function of MMPs, especially MMP-1, in EGFR-TKI–resistant lung adenocarcinoma." (PMID 29463039, 2018). "This study investigated differentially located EGFR expression in lung adenocarcinoma." (PMID 29950164, 2018). "Overexpression of EGFR in lung adenocarcinomas and TNBCs may provide one clue for common etiologic pathways." (PMID 30356721, 2018). "Patients with lung adenocarcinoma harboring common epidermal growth factor receptor (EGFR) mutations usually have a good response rate (RR) and longer progression-free survival (PFS) to EGFR tyrosine kinase inhibitors (TKIs)." (PMID 30428509, 2018). "To explore the utility of our approach, we focused on EGFR-mutant lung adenocarcinoma." (PMID 28287179, 2017). "The YAP1 inhibiting properties of statins and its ability to kill EGFR-mutant lung adenocarcinoma cells may provide some evidence explaining this interesting phenomenon." (PMID 29163769, 2017). "The mechanism(s) of acquired resistance after receiving afatinib as a first-line treatment for advanced EGFR mutation-positive lung adenocarcinoma is not clearly understood." (PMID 29163842, 2017). "In conclusion, our study suggests that high levels of PHLPP1 might predict a better survival of target therapy and a longer time before acquired resistance to EGFR-TKI in lung adenocarcinoma patients." (PMID 28938613, 2017). "Human lung adenocarcinoma H1975 cells, harboring an EGFR‐L858R‐sensitive mutation or an EGFR‐T790M‐resistant mutation, were resistant to the first‐generation EGFR‐TKI gefitinib, but were sensitive to the third‐generation EGFR‐TKI osimertinib." (PMID 29125233, 2017). "Recently, whole-genome sequencing analysis and immunohistochemical analysis for elucidation of the evolution of resistance were performed in specimens of advanced lung adenocarcinoma (LADC) with EGFR mutations, which subsequently transformed into SCLC after EGFR TKI treatment." (PMID 29140271, 2017). "Furthermore, the observed downregulation of EGFR suggests potential therapeutic application more broadly in cancer, including adenocarcinoma of the lung and glioblastoma multiforme." (PMID 29113288, 2017). "Preclinical data suggest that HSP90 inhibition could also be effective in cancers that acquired resistance to other targeted therapeutics, such as mutant EGFR-driven lung adenocarcinoma." (PMID 28032595, 2017). "EGFR L858R lung adenocarcinomas similarly share few alterations between tumors." (PMID 28231819, 2017).
lung adenocarcinoma (continued). "In the present case, concomitant afatinib with WBRT was feasible with achievement of rash palliation of symptoms and good, durable radiological response in an Exon19-del EGFR-mutant lung adenocarcinoma patient who progressed during TKI therapy with the manifestation of simultaneous brain and LM." (PMID 28540256, 2017). "The ER antagonist may well become a new and effective treatment modality for patients with lung adenocarcinoma and an alternative treatment for patients with acquired resistance to the EGFR antagonists." (PMID 28783064, 2017). "A 58 years old woman (never-smoker, ECOG PS 1) was diagnosed with stage IV lung adenocarcinoma, harboring both tumor tissue and plasma EGFR 19del mutation." (PMID 29340107, 2017). "However, Pelosi and co-workers found significant intra-tumour heterogeneity including co-existence of EGFR and KRAS mutations in minority clones using laser microdissection of multiple areas in lung adenocarcinomas." (PMID 28347348, 2017). "Pleural invasion rate was highest in peripheral lung adenocarcinoma, with patients harboring EGFR mutation showing significantly higher values (62.5%) compared with those without EGFR mutation (p = 0.018)." (PMID 28253871, 2017). "We present the first portrait of clinically actionable alterations in lung adenocarcinoma of Indian origin that includes EGFR, KRAS, EML4-ALK, AKT1, PIK3CA, FGFR4 and ERBB2, similar to that identified in other ethnic groups, and an additional subset of patients with FGFR3 mutations." (PMID 27998968, 2017). "We delineate the molecular mechanisms and signaling pathways by which PGE2 induces EGFR nuclear import and promotes nuclear EGFR-mediated gene transcription in lung adenocarcinoma cells, demonstrating a role for the prostanoid as a critical mediator of EGFR oncogenicity." (PMID 28415726, 2017). "Approximately 20% lung adenocarcinoma patients are Epidermal Growth Factor Receptor (EGFR) mutant." (PMID 28336963, 2017). "We therefore were interested in whether YAP1 inhibitions through other mechanisms can also affect EGFR-dependent lung adenocarcinoma cells." (PMID 29163769, 2017). "Therefore, we studied the effects of BRAFV600E, MET activation, and EGFRT790M, alone or in combination, on growth and therapeutic response in human EGFR-mutant lung adenocarcinoma cellular models." (PMID 28287179, 2017). "It is still unknown how the EGFR and ALK mutational profile affects the risk of DVT/VTE in lung adenocarcinoma." (PMID 28560038, 2017). "The EGFR gene affects the invasion capability of lung adenocarcinoma." (PMID 28253871, 2017). "The EGFR protein structure of this EGFR variant remains unchanged according to AASsites and has been detected before in Gefitinib treated lung adenocarcinoma patients without an association with survival." (PMID 28199979, 2017). "Autophagy is reported to be associated with resistance to afatinib, but its exact effect and mechanisms has not been clearly elucidated especially in lung adenocarcinoma with activating EGFR mutations." (PMID 28676644, 2017). "Interestingly, studies have found that the presence of driver genes, including EGFR and KRAS, are often associated with pathological subtypes in lung adenocarcinomas." (PMID 29137260, 2017). "The EGFR SNPs have a cumulative effect on decreasing the lung adenocarcinoma risk in non-smoking women with HRT." (PMID 28783064, 2017). "To assess if EGFR-MET interaction is modified by EGFR mutations, we first generated two novel cell lines by modification of the NCI-H1975 lung adenocarcinoma cell line that harbours L858R and T790M (L858R/T790M) mutant EGFR (to be referred to from here on as H1975L858R/T790M)." (PMID 28141869, 2017). "Targeting MAP4K4 could be a promising alternative mean of ERK pathway inhibition and MAP4K4 coinhibition could prevent or circumvent resistance to vertical inhibition of EGFR/RAS/RAF/MEK pathway in a broad range of patients with lung adenocarcinoma." (PMID 28306189, 2017).
lung adenocarcinoma (continued). "So, apatinib might be an optional choice for post-first-line treatment of EGFR wild-type advanced lung adenocarcinoma patients." (PMID 29029508, 2017). "One reason for the failure to directly target MYC, at least in SCLCs, is that, unlike the epidermal growth factor receptor mutations or anaplastic lymphoma kinase rearrangement in lung adenocarcinomas, MYC de-regulation is not a sole driver aberration." (PMID 28192473, 2017). "We recruited 75 patients with advanced lung adenocarcinoma receiving EGFR TKIs treatment." (PMID 28938613, 2017). "The search of mutation of EGFR and ALK and administration of appropriate targeted therapy could improve survival of patients with advanced lung adenocarcinoma." (PMID 28327204, 2017). "Given that many lung adenocarcinomas lacking EGFR/RAS/RAF mutations also displayed significant MAPK activation, it is reasonable to predict that there are additional, still undetected MAPK pathway regulators." (PMID 28306189, 2017). "The finding of ALK/EGFR coaltered lung adenocarcinoma cases may be explained by clonal evolutionary dynamics and the resulting complex clonal architecture of lung adenocarcinoma samples." (PMID 28887531, 2017). "Meanwhile, the suitability of the result for EGFR mutation remains unclear, and the prognostic value of MPP remains inconclusive in advanced-stage lung adenocarcinoma." (PMID 28380449, 2017). "Mutant EGFR activated Shp2 is essential for mutant EGFR driven lung adenocarcinoma." (PMID 28085101, 2017). "Recently, it has been shown that circulating miRNA-122 and miRNA-195 have prognostic value in predicting EGFR mutation and overall survival of female non-smokers with advanced stage lung adenocarcinoma." (PMID 29383112, 2017). "Molecular causal relationships between EGFR or KRAS mutation status and glucose metabolism were then elucidated in 62 lung adenocarcinomas using cap analysis of gene expression (CAGE), a method to determine and quantify the transcription initiation activities of mRNA across the genome." (PMID 28422979, 2017). "EGFR is overexpressed or aberrantly activated in many tumours including lung adenocarcinoma, suggesting that EGFR could serve as a target in the EV-based cancer drug delivery system." (PMID 28326166, 2017). "We explored this hypothesis by evaluating the response of three lung adenocarcinoma cell lines that differ only in their EGFR genotype to the MET inhibitor SGX523 in vitro and in a murine xenograft model derived from the same cells." (PMID 28141869, 2017). "High level of baseline CEA and decline 1 month after treatment could predict the efficacy of EGFR-TKIs in patients with advanced lung adenocarcinoma." (PMID 28935011, 2017). "Additional SRS could also yield a longer OS compared with administration of TKIs alone for EGFR-mutant lung adenocarcinoma patients with BM." (PMID 28076323, 2017). "There is an ongoing trial of comparing upfront erlotinib with WBRT at initial presentation to erlotinib alone with WBRT at disease progression in patients with EGFR-mutant lung adenocarcinoma with BM (clinicaltrials.gov ID NCT01763385), with mature data pending." (PMID 29340055, 2017). "In addition, the EGFR wild-type lung adenocarcinoma is probably an estrogen-dependent carcinoma, as a higher expression and potent poor prognosticator of aromatase and the ERβ in the group." (PMID 28783064, 2017). "From these results, we analyzed publicly available data to investigate whether sortilin expression could be affected by oncogenic drivers such as KRAS or EGFR amplification, as observed in lung adenocarcinoma." (PMID 29084952, 2017). "The identification of druggable driver mutations and rearrangements (e.g., EGFR mutations, ALK, ROS1 and RET-fusions) routinely detected in approximately 15% of NSCLCs has dramatically changed the therapeutic approach for lung adenocarcinoma in the last ten years." (PMID 29137348, 2017).